SPRY2 (sprouty RTK signaling antagonist 2)
Diseases named in the same sentence as SPRY2 in open-access papers (continued):
Sharing a sentence is not in itself a finding about the gene and the disease.
tumor (84 papers, 2010 to 2025). "Although SRB1 is a bidirectional cholesterol transporter, SPRY2‐deficient tumour cells take up more and efflux less cholesterol." (PMID 29540470, 2018). "Along with altered circulating cholesterol levels, in mice bearing SPRY2‐deficient tumours, serum IL6 levels were also significantly raised following ADT." (PMID 29540470, 2018). "Mechanistically, HER2‐IL6 signalling axis enhances the expression of androgen biosynthetic enzyme HSD3B1 and increases SRB1‐mediated cholesterol uptake in SPRY2‐deficient tumours." (PMID 29540470, 2018). "Mechanistically, loss of the tumour suppressor SPRY2 leads to activation of the HER2‐IL6 cytokine signalling axis, which enhances tumoral expression of androgen biosynthetic enzyme HSD3B1 and lipoprotein receptor SRB1." (PMID 29540470, 2018). "Similar to the reported effectiveness of statins in inhibiting the progression of LNCaP tumours to CRPC state, we show that decreasing cholesterol bioavailability using statin treatment sensitised SPRY2‐deficient tumours to ADT." (PMID 29540470, 2018). "Compared to Nsi orthografts, SPRY2‐deficient orthografts showed sustained growth under ADT conditions with minimal ADT‐induced tumour necrosis (and EV2J)." (PMID 29540470, 2018). "Mechanistically, the HER2‐p38 signalling axis drives progression of SPRY2‐deficient tumours to an androgen autonomous castration‐resistant state by inducing IL6 cytokine axis." (PMID 29540470, 2018). "This analysis also suggests opposing roles in tumor susceptibility for Map2k4 and Spry2, genes that exert opposite effects on mitogen-activated protein kinase (MAPK) signaling." (PMID 21244661, 2011). "The authors suggest that these non-responder patients may therefore be susceptible to metastasis due to delayed tumor surgical resection and in part by increased SPRY2 expression." (PMID 34685612, 2021). "Since SPRY2 expression was progressively lost from HN state to CRPC, we hypothesised that SPRY2 deficiency may modulate tumour response to ADT." (PMID 29540470, 2018). "Our work implicates a central role of IL6 in HER2‐mediated CRPC in SPRY2‐deficient tumours." (PMID 29540470, 2018). "Our work suggests that in SPRY2‐deficient tumours IL6 may mediate AR‐dependent CRPC formation by facilitating tumoral androgen biosynthesis, at least in part through enhanced androgen biosynthesis." (PMID 29540470, 2018). "Whether D4A, a pan inhibitor of androgen biosynthetic enzymes, sensitised CRPC with high HSD3B1 expression (e.g., SPRY2‐deficient CRPC tumours) to ADT requires further investigation." (PMID 29540470, 2018). "Since the overexpression of Spry2 did not alter KRAS mutational frequencies, it was suggested that the tumor-suppressing activity of the overexpressed Spry2 might be applied at stages of carcinogenesis subsequent to KRAS mutation." (PMID 24744103, 2014). "Thus, SPRY2 deficiency‐driven p38‐IL6 signalling axis may support resistance to ADT by promoting self‐sufficiency for androgens within the tumour, at least in part, through increased levels of intra‐tumoral cholesterol required for androgen biosynthesis." (PMID 29540470, 2018). "MiR-21 is also increased in NB tissue compared with matched adjacent non-tumor tissue and reduces SPRY2 protein in NB cells." (PMID 41516252, 2025). "Although inhibition of miR-21 increases the SPRY2 protein in GB cells, inhibition of miR-21 reduces proliferation and invasion of GB cells and reduces tumor growth in intracranial rat and mouse GB xenograft models." (PMID 41516252, 2025).
tumor (continued). "Conversely, gain of cg16766325 methylation in the promoter region of SPRY2, a tumor suppressor with endogenous inhibitory activity for the RAS/MAPK pathway, was associated with decreased SPRY2 mRNA expression." (PMID 40705465, 2025). "Together, there is evidence that SPRY1 and -2 are oncogenes in GB, whereas SPRY2 is a tumor suppressor in NB." (PMID 41516252, 2025). "Overexpression of SPRY2 in low tumorigenic U251 cells promotes tumor growth of subcutaneous mouse xenografts." (PMID 41516252, 2025). "MiR-27a and -27b are increased in tumor tissue from GB patients compared to normal brain tissue, and both miRs reduce the SPRY2 protein in GB cells." (PMID 41516252, 2025). "The inhibitory effect of SPRY2 knockdown on tumor growth has been demonstrated in vivo using subcutaneous and intracranial mouse tumor xenograft models of U87 cells." (PMID 41516252, 2025). "In NB, SPRY2 acts as a tumor suppressor, whereas the effects of SPRY1, -3, and -4 in NB have not been investigated so far, although the survival analysis revealed increased survival of NB patients with low SPRY3 levels in different datasets." (PMID 41516252, 2025). "Cell viability of U251 cells overexpressing FGFR1-EGFP was strongly increased by SPRY2-OE even after cisplatin treatment, which confirms our previous study that SPRY2-OE increases tumor growth of U251 xenografts in mice." (PMID 39682716, 2024). "This study highlighted the significance of EBV‐miR‐BART1‐5p in NPC VM and angiogenesis, and revealed Spry2 as an important regulator of tumor VM and angiogenesis." (PMID 37097161, 2023). "HE, Masson staining and Ki-67 IHC staining showed more matrix deposition and tumor proliferation after SPRY2 knockdown." (PMID 37507768, 2023). "We next explored the prognostic value of SPRY2 protein and found the correlation between low SPRY2 expression in CAFs and patients’ higher frequency of survival event, larger tumor size and higher AJCC stage." (PMID 37507768, 2023). "We then used a direct-contact co-culture model to observe the effect of fibroblast-expressing SPRY2 on tumor cell growth." (PMID 37507768, 2023). "Another lncRNA, CASC2, acts as a tumor suppressor in human malignancies, serving as a ceRNA for miR-183 and positively amplifying the expression of another tumor suppressor, SPRY2, a key antagonist of receptor tyrosine kinase signaling." (PMID 38137905, 2023). "Our findings elucidated that lactate production by SPRY2 knockdown in stromal fibroblasts promotes tumor cell stemness." (PMID 37507768, 2023). "Functionally, SPRY2 knockdown in fibroblasts enhanced the stemness of tumor cell dependent on glycolysis in fibroblasts." (PMID 37507768, 2023). "SPRY2 deregulation has been found in various cancer types and exhibited to affect tumor development, progression, and metastasis." (PMID 36749775, 2023). "Silencing SPRY2 largely compromised the tumor-suppressive effect of HOXA5 in PCa progression and cancer stemness." (PMID 37845209, 2023). "Recently, Spry2 was further attributed great regulatory roles in cell proliferation, survival, migration and angiogenesis, attracting attention in the field of tumor progression." (PMID 37097161, 2023). "Co-treatment with miR-21-5p and reversine effectively inhibited the malignancy of HBC cells by downregulating SPRY2 expression, thereby suggesting that SPRY2 is an anti-tumor gene in HBC." (PMID 34967265, 2022). "MicroRNA mediated downregulation of SPRY2 has been observed in several cancers affirming its tumor suppressor properties." (PMID 35386334, 2022). "Spry2 contributes to the modulation of tumor cell invasion by regulating the mitogen-activated protein kinase (MAPK) signaling axis." (PMID 35071748, 2022).
tumor (continued). "Our study revealed that reversine and the selected miR-21-5p inhibitor synergistically exert tumor-suppressive effects on HBC cells by targeting SPRY2." (PMID 34967265, 2022). "SPRY2 – sprouty RTK signaling antagonist 2 – has been known as a tumor suppressor by preventing ERK and AKT signaling activation." (PMID 34101054, 2021). "Accordingly, Spry2 and/or Spry4 are shown to act as tumor-suppressors in cancer originated from, e.g., lung, liver, breast, prostate and bone." (PMID 31374860, 2019). "Compatible with the tumor-promoting function of Spry2 in brain, the Spry proteins are important for other neuronal processes." (PMID 31374860, 2019). "In other types of tumors, members of the Spry protein family fulfill a tumor-promoting task as it was demonstrated for Spry2 in colon carcinoma and for Spry1 in rhabdomyosarcoma." (PMID 31374860, 2019). "SPRY2, a gene with reduced function in half of human HCCs, is known to act as a tumor suppressor in the development of liver cancer via inhibition of the Ras signaling pathway." (PMID 31861541, 2019). "The potential tumor suppressive role of Spry2 in HCC was investigated by expressing a dominant negative form of Spry2 (Spry2Y55F) and an activated β-catenin in mouse liver through hydrodynamic injection and the SB transposon system." (PMID 31861541, 2019). "In tumor cells and primary embryonic fibroblasts, Spry2 increases the amount of PTEN and decreases its phosphorylation, thereby enhancing the activity of PTEN to suppress phosphorylation of Akt." (PMID 32038175, 2019). "As tumour differentiation is an important factor determining tumour invasion, we investigated the role of SPRY2 on ICC cell migration and invasion." (PMID 30160357, 2018). "Despite an initial favourable response to ADT (achieved by castration), dual heterozygous loss of Pten and Spry2 led to CRPC, signified by comparable tumour burden and overall survival in mock and ADT‐treated mice (and EV1D–F)." (PMID 29540470, 2018). "The correlation between SPRY2 and clinicopathological factors was analysed with Chi‐Square test to screen the potential tumour progression processes influenced by SPRY2." (PMID 30160357, 2018). "We further detected the SPRY2 expression in the tumor of HepG2anti-miR-330-5p cells by immunohistochemical staining, the representative images showed the markedly increased positive staining of SPRY2 compared with control tumor." (PMID 30464168, 2018). "We next studied CWR22Res SPRY2 KD generated orthografts to investigate the role of SPRY2 in tumour response to ADT (Fig EV2G)." (PMID 29540470, 2018). "SPRY2 had relatively higher mRNA level compared with other SPRY members and its mRNA level in adjacent tissues was significantly higher than in tumour tissues, suggesting the potential tumour‐suppressing role of SPRY2 in ICC oncogenesis." (PMID 30160357, 2018). "With Chi‐Square test, we demonstrated that poorly differentiated cases appeared to have lower SPRY2 expression, so we further stratified the test cohort according to tumour differentiation and compared the SPRY2 expression." (PMID 30160357, 2018). "For these reasons, it has been suggested to use Spry2 protein levels as a prognostic marker and Spry proteins have been dubbed “tumor suppressors”." (PMID 28196140, 2017). "This suggests a degree of redundancy in the sprouty tumour suppressors, with Spry2 possibly being compensatory in this context." (PMID 26075267, 2015). "Ectopic expression of SPRY2 in cell lines derived from non-small cell lung carcinoma tissues significantly reduced proliferation and tumour formation of subsequent xenografts." (PMID 26075267, 2015). "SPRY1 mRNA and protein levels are increased in lung cancer tissue while SPRY2 and 4 levels are decreased and they function as tumor suppressors in these tumor." (PMID 26392417, 2015). "The ability of SPRY2 to inhibit MAPK/ERK signaling pathway activation suggested that SPRY2 functions as a tumor suppressor gene in MM cells." (PMID 25825239, 2015).
tumor (continued). "Collectively, they demonstrated that Spry2 downregulation contributes to NSCLC tumorigenesis via ERK-dependent and ERK-independent mechanisms and implicated Spry2 as a tumor suppressor in NSCLC." (PMID 24744103, 2014). "Although the highest Spry2 expression levels were observed in those tumours with low HER2 gene expression, there was still a wide range of expression of Spry2 in HER2-high tumours." (PMID 21909357, 2011). "However, in our subsequent study, we need to further verify the role of SPRY2, the target gene of miR-27a-3p, in the malignant biological behavior of tumor cells and the differentiation of macrophages which is now supported by the literature." (PMID 39742261, 2024). "The identification of biomarkers, such as SPRY2 and IL-1 from our upstream regulator analysis, can suggest mechanisms of tumor proliferation and approaches for adjuvant therapy, due to the potential of such proteins to become eventual targets for drug repositioning." (PMID 37047796, 2023). "Our study is the first to reveal that SPRY2 targeted by miR-21-5p could play an anti-tumor role in HBC cells, hence providing a novel target for HBC therapy." (PMID 34967265, 2022). "SPRY1 and SPRY2 were among the most highly down-regulated genes in normal-adjacent regions when compared with normal controls and remained down-regulated in dysplasia and tumor." (PMID 35394843, 2022). "SPRY1 and SPRY2 were shown to be downregulated in a variety of cancers, including liver, prostate, and lung tumors, implying a unique tumor-suppressive function.﻿ Conversely, SPRY1′s high expression in tumors harboring Ras/Raf mutations to tumor progression suggests its role in cancer malignancy." (PMID 35910677, 2022). "Of note, the expression of previously well-established in vitro targets of miR-21 having tumor-suppressive activity, i.e., Ppara, Pdcd4, Timp3, Spry2, Pten, and Hbp1, was unchanged with miR-21 deficiency in vivo in mice again highlighting a cell/organ context-dependent action of miR-21." (PMID 34638467, 2021). "Spry2 is frequently found to function as tumor suppressor in cancers of e.g., lung, breast, and liver), but in other tumor entities it exerts tumor promoting tasks (e.g., in colon and brain cancers)." (PMID 34769378, 2021). "Concerning effects on tumor growth, the precise role of SPRY2 in CRC remains controversial as one study has reported SPRY2 functions as a tumor suppressor, whereas our previous studies have suggested SPRY2 might function as an oncogene by promoting EMT." (PMID 34685612, 2021). "Moreover, SPRY2 has also been reported to be a critical regulator in MM and exert its tumor-suppressing roles by inhibiting cell proliferation, survival, and metastasis." (PMID 30837325, 2019). "Besides, SPRY2 has also been identified as a crucial negative regulator of multiple tumor-driving signaling pathways, such as ERK1/2, Smad2 and EGFR pathways." (PMID 30837325, 2019). "Furthermore, SPRY2 has been reported to serve as a tumor suppressor in MM by repressing cell proliferation, survival, and motility." (PMID 30837325, 2019). "Pathway analysis revealed many DE upregulated genes arising from SPRY2 KO to be involved with DNA replication and cell cycle regulation; this is consistent with the established role for SPRY2 in inhibiting cell proliferation and acting as a tumour suppressor in certain types of cancer." (PMID 31664995, 2019). "With wound healing assay, we proved that FGFR2 knockdown notably impaired the tumour cell migration while silencing SPRY2 could promote migration of RBE or HuCCT‐1 cells." (PMID 30160357, 2018). "This is the first study on the tumour‐suppressing function of SPRY2 in ICC as far as we know." (PMID 30160357, 2018). "SPRY2 also exhibits contrasting tumor suppressive or oncogenic roles in different cancer contexts." (PMID 29445192, 2018). "The phosphorylation of SPRY2‐Y55 was required in this tumour‐suppressing function of SPRY2." (PMID 30160357, 2018).
tumor (continued). "Several studies have demonstrated that Spry2 could inhibit growth factor-induced cell proliferation and migration and acted as a tumor suppressor in many types of cancer." (PMID 30464258, 2018). "Thus, SPRY2 functions to maintain MET levels in multiple tumor types, although the precise mechanism is unclear." (PMID 29445192, 2018). "Hence, there is a reciprocal cross talk between the “tumor suppressor”, Spry2, and “tumor promoters”, HIF1α/HIF2α." (PMID 28196140, 2017). "Hence, targeting HIF1α and HIF2α in tumors would not only suppress the “tumor promoting” actions of these transcription factors but by elevating SPRY2 gene transcription, elevate Spry2 protein levels and, therefore, the tumor suppressing actions of Spry2." (PMID 28196140, 2017). "Recently, we demonstrated that one of the mechanisms by which Spry2 exerts its “tumor suppressor” functions is by decreasing the stability of HIF1α and HIF2α with a corresponding decrease in their ability to alter transcription of the HIF1α and HIF2α target genes." (PMID 28196140, 2017). "Given the highly context-dependent and cell-type-specific nature of FGFR1 signaling, and its interaction with SPRY2 and other RTKs as we have observed, its function may change drastically during neoplasia development." (PMID 27046834, 2016). "Importantly, patients with lower tumor SPRY2 expression have significantly poorer overall survival and disease-free survival than those with high SPRY2 expression." (PMID 27835572, 2016). "Interestingly, in a context- and/or tissue-dependent manner, SPRY2 has been shown to act as a tumor suppressor or promoter." (PMID 27835572, 2016). "Indeed, concomitant loss of Spry1 and Spry2 function results in tumorigenesis with significant PIN and invasive tumours only induced by codeletion of Spry1 and Spry2 in haploinsufficient phosphatase and tensin (Pten) mice." (PMID 26075267, 2015). "Furthermore, reduction of Spry2 expression is correlated with tumor progression in the MMTV-PyMT mouse model." (PMID 24718286, 2014). "The first group suggests that some members of this protein family, in particular Spry2, may have a tumor suppressing potential." (PMID 23251157, 2012). "Considering the decreased expression of Spry2 in high grade tumors in comparison with low-grade carcinomas, they suggested that Spry2 could act as a “tumor progression” suppressor gene." (PMID 23251157, 2012). "Higher grade tumours had lower expression of Spry1 and Spry2." (PMID 21909357, 2011). "However, novel tumor-specific eQTL are detected for several genes associated with tumor susceptibility, including IL18 (Il18), Granzyme E (Gzme), Sprouty homolog 2 (Spry2), and Mitogen-activated protein kinase kinase 4 (Map2k4)." (PMID 21244661, 2011). "Furthermore, SPRY2 promotes tumor growth of GBM mouse xenograft models." (PMID 39682716, 2024). "Furthermore, we found that endogenous expression of Spry2 in 15 NPC tissue specimens was prominently reduced in comparison with 15 NP tissue specimens, demonstrating Spry2 might function as a tumor suppressor in NPC." (PMID 37097161, 2023). "We next test whether SPRY2 downregulation in the TME controls tumor progression." (PMID 37507768, 2023). "Thus, C-MET, CDKN2A, P-glyc (ABCB1) and N-cadherin displayed significantly lower protein expression levels in HGSOC tumors corresponding to PARPis-sensitive AsPCs, while FANCF and SPRY2 showed stronger expression in the PARPis-sensitive AsPCs-matched tumor samples." (PMID 33213473, 2020). "In addition, xenograft model was established to evaluate SPRY2 role in tumor growth." (PMID 28002800, 2017). "However, the mechanisms involved in SPRY2-mediated tumor suppression remain unknown and require further investigation." (PMID 27835572, 2016). "This study suggested that Spry2 might function as a tumor suppressor in HCC." (PMID 24744103, 2014).